ARID1B (AT-rich interaction domain 1B)
Diseases named in the same sentence as ARID1B in open-access papers (continued):
Sharing a sentence is not in itself a finding about the gene and the disease.
lung carcinoma (6 papers, 2017 to 2025). "In conclusion, our study expands the understanding of the mechanisms by which ARID1B mutation influences the response to ICIs in lung cancer patients." (PMID 38577613, 2024). "Here, we observed a significant association between ARID1B mutation and improved overall survival in lung cancer patients treated with ICIs, consistent with previous studies." (PMID 38577613, 2024). "Knocking out ARID1B enhanced the susceptibility of two subtypes of non-small cell lung cancer cells to T cell-mediated cytotoxicity, and knocking out ARID1B increased the number of lung cancer cells dying when co cultured with T cells in both subtypes of non-small cell lung cancer." (PMID 38577613, 2024). "ARID1B is differentially expressed in lung cancer and normal tissues, and its expression level being lower in cancer cells." (PMID 40210476, 2025). "We induced DNA damage in SK-MES1 and H2030 lung cancer cells, which are ARID1B wild type cells, with etoposide, a known DNA-damaging agent." (PMID 38577613, 2024). "In our study, we focused on the impact of ARID1B mutation, a core member of the SWI/SNF complex, on the response to ICIs in lung cancer patients." (PMID 38577613, 2024). "ARID1B knockdown in lung cancer cell lines enhances DNA damage, impairs DNA repair, alters chromatin accessibility, and activates the cGAS-STING pathway." (PMID 38577613, 2024). "Three genes (TET1, ARID1B, and BAZ1A) are highly mutated in breast and lung cancer types, whereas TET1, IDH2, and ARID1B were also among the top genes altered in several cancer types, further corroborating their putative role as cancer drivers." (PMID 32963031, 2020).
myopia (6 papers, 2019 to 2026). "Additionally, we confirmed our previous findings that patients with ARID1B-related disorder have a risk of seizures, myopia, nephrolithiasis, hypothyroidism, diabetes mellitus type 2, and scoliosis." (PMID 39669611, 2024). "In contrast, ARID1B-ID patients presented a series of features such as myopia, cryptorchidism, sleep apnea, attention-deficit hyperactivity disorder, and a high pain threshold." (PMID 41545737, 2026). "Suggestive features for an ARID1B-related disorder in this case are hypoplasia of the corpus callosum, myopia, seizures and scoliosis." (PMID 34440449, 2021). "It was found that high myopic associated proteins (ASXL1 FGFR3 ERBB3 SOX4) can affect ARID1B protein by affecting ARIDIA protein, and COL2A1 protein can also affect ARIDIA protein by affecting FGFR3 protein, resulting in the clinical phenotype of patients with high myopia." (PMID 38790056, 2024). "Therefore, we predict that mutations in the ARID1B gene would result in decreased expression of wild-type protein, relatively enhanced activity of ARIDIA protein, low expression of FGFR3 protein, and low expression of COL2A1 protein leading to clinical phenotypes associated with myopia." (PMID 38790056, 2024). "Analysis of protein interactions in the STRING online database revealed that the ARID1A protein interacts with the high myopia gene-related proteins FGFR3, ASXL1, ERBB3, and SOX4, whereas the ARID1A protein antagonizes the ARID1B protein." (PMID 38790056, 2024).
hepatocellular carcinoma (5 papers, 2014 to 2020). A malignant tumor that arises from hepatocytes. "In summary, this case-control study suggested the potentially functional variant in ARID1B, rs73013281, as a new genetic susceptibility factor for hepatocellular carcinoma (HCC), especially in interaction with physical activity." (PMID 28415691, 2017). "Alterations in ARID1B and other chromatin regulators in hepatocellular carcinoma (HCC) predict degree of liver fibrosis and hepatic vein invasion, suggesting these genes may drive poor prognosis in some tumors." (PMID 33105726, 2020). "However, it had remained unknown whether or not genetic variants of ARID1B involved in development of hepatocellular carcinoma (HCC)." (PMID 28415691, 2017).
melanoma (5 papers, 2019 to 2023). A malignant, usually aggressive tumor composed of atypical, neoplastic melanocytes. "A study in which targeted next generation sequencing was conducted on 38 treatment naive melanoma patients also found ARID1B to be mutated at the same rate as ARID1A (13.2%)." (PMID 35323214, 2022). "The unique functions of ARID2 compared to the other ARIDs (ARID1A and ARID1B) will increase understanding of why ARID2 is more frequently mutated in melanoma." (PMID 35323214, 2022). "In light of accumulated data, ARID2, ARID1B, SMARCA4 (BRG1), and SMARCA2 (BRM) have the most important mutations in melanoma." (PMID 36844227, 2023). "It will be important to elucidate the functions of ARID1A and ARID1B both during melanocyte development and in melanoma models, and to elucidate how they regulate enhancer function to regulate gene expression." (PMID 35323214, 2022). "However, a meta-analysis of mucosal melanomas suggests that copy number losses in ARID1B (33.3%) occur more frequently than in ARID1A (8.3%) for this melanoma sub-type." (PMID 35323214, 2022). "Interestingly, SMARCA2 and ARID1B alterations were mainly homozygous deletions, possibly because they map to chromosomes 9p and 6q, respectively, which are commonly affected by arm-level losses in melanoma, whereas alterations of other genes constituted indels and SNVs." (PMID 35706047, 2022). "Loss-of-function mutations in the components of the SWI/SNF complex such as AT-rich interactive domain-containing protein 1A (ARID1A), ARID1B, ARID2, or SMARCA4 are common in melanoma, suggesting that altered chromatin remodeling plays a role in the pathogenesis of this disease." (PMID 36844227, 2023). "Since 10.67% of melanoma patients have altered ARID1A, this may be useful in identifying ARID1B as a potential therapeutic target in patients with ARID1A loss or alteration." (PMID 36844227, 2023). "Although there have not been any functional studies of ARID1B in melanoma, other cancer cells with mutations in ARID1A are highly vulnerable to ARID1B loss." (PMID 35323214, 2022). "Moreover, in vitro studies have shown that several genes are linked to melanomagenesis in the co-deleted region, including ARID1B, CCNC, and ROS1, although none have yet been shown to be functionally important in melanoma in vivo." (PMID 34140478, 2021).
ovarian clear cell cancer (5 papers, 2014 to 2025). An invasive malignant neoplasm that arises from the ovary and is characterized by a predominance of clear and hobnail malignant epithelial cells. "For example, the BRD2 inhibitor, JQ1, can suppress ARID1A-deficient ovarian clear cell cancer cells because BRD2 inhibition decreases ARID1B transcription." (PMID 36371186, 2022). "A synthetic lethal relationship between ARID1A and ARID1B has previously been observed for proliferation of ovarian clear cell carcinoma cells (OCCCs)." (PMID 28967863, 2017). "ARID1B function at enhancers is conserved in ARID1A mutant ovarian clear cell carcinoma cells." (PMID 28967863, 2017). "Unlike ovarian clear cell carcinoma, cervical adenocarcinomas, and gastric carcinoma, SCLC harbored a relatively low frequency of ARID1A and ARID1B mutations." (PMID 41049615, 2025). "(J) k-means clustering of 4878 differentially expressed genes in TOV21G cells expressing shRNAs to scrambled control (scrambled) or ARID1B (ARID1B KD1, KD2) from two independent biological replicates compared to expression in ovarian clear cell carcinoma versus normal ovaries (CC vs WT Ovary)." (PMID 28967863, 2017).
bladder cancer (4 papers, 2019 to 2025). "In addition, bladder cancer patients harboring ARID1B mutations (P = .0451) could achieve a better prognosis with ICI therapy." (PMID 35239432, 2022). "Suppressing the expression of ARID1B can significantly reduce the proliferation, migration, and invasive ability of bladder cancer cells." (PMID 39779467, 2025). "ARID1B, as a homologous subunit of ARID1A, can potentially serve as a target for ARID1A‐mutated bladder cancer." (PMID 39779467, 2025). "In a prognostic study by Beihe Wang on bladder cancer and Yan Cui's research on triple‐negative breast cancer, ARID1B was associated with poor prognosis." (PMID 39932052, 2025). "Consistent with our study, Wang and colleagues demonstrated that ARID1B depletion inhibits proliferation in bladder cancer cell lines without ARID1A mutation." (PMID 31796878, 2019). "Inhibiting the expression of ARID1B significantly reduces the proliferation, migration and invasive ability of bladder cancer cells, suggesting that it could serve as a potential prognostic biomarker for urothelial carcinoma of the bladder and aid in patient selection for adjuvant chemotherapy." (PMID 39779467, 2025).
depression (4 papers, 2017 to 2023). "KDM6B and ARID1B have been demonstrated to be important in the regulation of depression." (PMID 37235790, 2023).
gastric cancer (4 papers, 2020 to 2025). A primary or metastatic malignant neoplasm involving the stomach. "However, the impact of ARID1B mutations on immunotherapy for gastric cancer still needs further exploration." (PMID 38890392, 2024).
Hydrocephalus (4 papers, 2017 to 2023). Hydrocephalus is an active distension of the ventricular system of the brain resulting from inadequate passage of CSF from its point of production within the cerebral ventricles to its point of absorption into the systemic circulation. "There was an increased incidence of hydrocephaly in the Arid1b+/− mice compared to other mice in both the Sacramento and Toronto colonies." (PMID 33757588, 2021). "The result suggests that hydrocephalus occurs significantly in Arid1b hKO mice (p = 0.0041, Fisher’s exact test)." (PMID 28867767, 2017). "16/272 (6.6%) of Arid1b+/- mice had hydrocephalus, the displacement of brain parenchyma by accumulated cerebrospinal fluid, a condition that frequently accompanies Dandy-Walker malformations seen in CSS patients." (PMID 28695822, 2017). "Of the 82 Arid1b+/+ used in this study, only one was excluded due to hydrocephalus (1.2%)." (PMID 33757588, 2021). "Hydrocephalus has been previously reported in Arid1b+/− mice models at rates of 5.5% to 6.6%." (PMID 33757588, 2021). "In addition, BAF mouse models showing hydrocephalus were established for Smarca4/Brg1 and Arid1b." (PMID 37219662, 2023).
medulloblastoma (4 papers, 2013 to 2022). A malignant, invasive embryonal neoplasm arising from the cerebellum. "In addition, the method identified the PDCD1LG2/CD274 region, 17p13.3, a region that has been implicated as a tumor-suppressor region in medulloblastoma, where it is deleted in 40% of cases and ARID1B, a member of the SWI/SNF chromatin remodeler complex implicated in differentiation and development." (PMID 23531283, 2013).
meningioma (4 papers, 2019 to 2026). A generally slow growing tumor attached to the dura mater. "Overall, WHO grade 1 meningiomas harbored numerous and heterogeneous genetic variants, which most frequently affected the NF2 (47%) gene and to a less extent the PNMA6A (22%), TIGD1 (16%), SMO (13%), PTEN (13%), CREG2 (9%), EEF1A1 (6%), POLR2A (6%), ARID1B (3%), and FAIM3 (3%) genes." (PMID 34868937, 2021).
microcephaly (4 papers, 2014 to 2025). A congenital or acquired developmental disorder in which the circumference of the head is smaller than normal for the person's age and sex. "Firstly, SOX11 mutant patients with microcephaly tend to be associated with oculomotor apraxia or abnormal eye morphology, while the ARID1B-related CSS patients usually have a coarse face." (PMID 35938035, 2022). "Conversely, haploinsufficiency of ARID1B (also known as BAF250B), a mutually exclusive paralog of ARID1A, similarly results in microcephaly, implying antagonistic roles in NSPC proliferation—with ARID1A-BAF functioning as a repressor and ARID1B-BAF as an activator." (PMID 41283518, 2025).
schwannoma (4 papers, 2017 to 2026). A benign, usually encapsulated slow growing tumor composed of Schwann cells. "An exome study in humans found that 37/125 (29%) of schwannomas have NS mutations in ARID1A or ARID1B." (PMID 38232086, 2024). "In recent study addressing the genomic landscape of schwannoma, 23% (23/99) of schwannoma harbored ARID1B mutations, in which only one mutation was frameshift deletion and others are missense mutations or non-frameshift indels." (PMID 28521285, 2017). "Other recurrently altered genes reported in schwannomas include LATS1, LATS2, ARID1A, ARID1B and DDR1." (PMID 41300852, 2025).
endometrioid carcinoma (3 papers, 2014 to 2022). "IHC staining of 6 EC cases (5 endometrioid carcinoma and 1 carcinosarcoma) with DICER1 hotspot mutations only identified ARID1A loss in one endometrioid carcinoma case, but neither SMARCA4 nor ARID1B was lost in any of the 6 cases." (PMID 33052929, 2020).
Laryngomalacia (3 papers, 2019 to 2021). Laryngomalacia is a congenital abnormality of the laryngeal cartilage in which the cartilage is floppy and prolapses over the larynx during inspiration. "Except for laryngomalacia and excessive salivation and/or drooling, all characteristics enriched in ARID1B patients in DECIPHER had been included in our questionnaire." (PMID 30349098, 2019). "During this study, it became evident from literature and the DECIPHER database that previously unknown features, such as laryngomalacia, were part of the ARID1B spectrum and should have been added to our questionnaire." (PMID 30349098, 2019).
lung adenocarcinoma (3 papers, 2020 to 2024). A carcinoma that arises from the lung and is characterized by the presence of malignant glandular epithelial cells. "Additionally, a large-scale data analysis of lung adenocarcinoma confirmed that ARID1B mutations are a major reason for the sensitive response of lung adenocarcinoma patients to immunotherapy." (PMID 38890392, 2024). "ARID1A or ARID1B expression was related to immunosuppression in 517 lung adenocarcinoma (LUAD) samples and 501 lung squamous cell carcinoma (LUSC) samples, which is mainly characterized by significant reductions in the abundances of activated CD8+ T cells and activated dendritic cells (DCs)." (PMID 32791957, 2020).
non-small cell lung carcinoma (3 papers, 2021 to 2025). A group of at least three distinct histological types of lung cancer, including non-small cell squamous cell carcinoma, adenocarcinoma, and large cell carcinoma. "This highlights the potential of ARID1B mutation as a predictive biomarker for immunotherapy outcomes in non-small cell lung cancer (NSCLC) patients." (PMID 38577613, 2024). "However, whether ARID1B deficiency affects the proliferation, migration and invasion abilities of non-small cell lung cancer (NSCLC) cells and its molecular mechanisms remain poorly understood." (PMID 40210476, 2025). "We investigated the apoptotic response of arid1b-knockdown non-small cell lung cancer (NSCLC) cells, and the results indicated that the reduction of arid1b did not influence the cellular apoptosis." (PMID 38577613, 2024).
Papillary thyroid cancer (3 papers, 2021 to 2025). "Papillary thyroid cancer was reported in a patient with an interstitial 6q25 deletion, including ARID1B." (PMID 34706719, 2021). "Among these, N Agrawal’s highly co-cited work, ‘Integrated genomic characterization of papillary thyroid carcinoma’, reveals recurrent mutations in key epigenetic regulatory genes, such as MLL, ARID1B, and MLL3, highlighting their potential role in thyroid cancer development." (PMID 38949925, 2024).
squamous cell carcinoma (3 papers, 2021 to 2022). A carcinoma arising from squamous epithelial cells. "Additionally, ARID1A and ARID2 mutations were more frequently found in males, SMARCA4 was more frequently mutated in patients with adenocarcinoma, and the ARID1B mutation was more frequently found in patients with squamous carcinoma, which were all statistically significant." (PMID 34512623, 2021).
triple-negative breast carcinoma (3 papers, 2019 to 2022). An invasive breast carcinoma which is negative for expression of estrogen receptor (ER), progesterone receptor (PR), and human epidermal growth factor receptor 2 (HER2). "Previous studies observed an increased expression of ARID1B in triple-negative breast cancer and breast invasive ductal carcinoma." (PMID 36313455, 2022).
adenoma (2 papers, 2021 to 2024). A neoplasm arising from the epithelium. "As with ARID2, the TSG and candidate drivers of colorectal adenomas ARID1A, and ARID1B are frequently mutated in MSI tumours including adenomas." (PMID 34843512, 2021).
breast invasive ductal carcinoma (2 papers, 2022 to 2025). "Another study of invasive ductal breast carcinoma showed that high ARID1B expression is linked to significantly lower 5-year disease-free survival compared to tumors with low expression." (PMID 40806597, 2025).
colon cancer (2 papers, 2022). "In the current study, we evaluated DNA methylation and gene expression profiles of ARID1B in colon cancer samples from TCGA." (PMID 36313455, 2022). "The expression of the ARID1B gene in colon cancer was hypermethylated in cancer samples than normal samples." (PMID 36313455, 2022). "Colon cancer cell lines showed a low mRNA ARID1B expression compared to colon normal cell line." (PMID 36313455, 2022). "Interestingly, RNA-seq data validated that ARID1B upregulated several immune pathways in colon cancer tissue." (PMID 36313455, 2022). "Furthermore, the HPA tool was used for protein expression analysis and ARID1B protein was decreased in colon tumor cells than endothelial cells and glandular cells." (PMID 36313455, 2022). "However, the prognosis significance of ARID1B and its methylation in colon cancer need to be clarified." (PMID 36313455, 2022). "These consistent results of aberrantly silenced ARID1B provide strong evidence that low ARID1B expression is an important indicator of the poor prognosis of COAD and the epigenetic changes might be a potentially increased risk of colon cancer-related death." (PMID 36313455, 2022). "Despite very little was found in the literature on the analysis of ARID1B expression and its DNA methylation in cancer, none of these studies was related to colon cancer." (PMID 36313455, 2022). "Additionally, the expression of ARID1B was positively correlated with the expression of three methyl transferases (DNMT1, DNMT3A, and DNMT3L) in colon cancer, although the difference was not significant." (PMID 36313455, 2022).
epilepsies (2 papers, 2013 to 2020).
growth deficiency (2 papers, 2015 to 2017). "In addition, some non-syndromic patients with missense mutations in ARID1B exhibited growth deficiency due to partial GH deficiency." (PMID 28695822, 2017).
hepatoblastoma (2 papers, 2021 to 2022). Hepatoblastoma (HB) is a malignant hepatic tumor and is the most common pediatric liver cancer. "The regulator of HOX‐AS2 is the chromatin remodeling factor ARID1B, suggesting an important role for the ARID1B/HOXA‐AS2/HOXA3 network in hepatoblastoma." (PMID 35592755, 2022).
hypothyroidism (2 papers, 2019 to 2024). Abnormally low levels of thyroid hormone. "Our data suggest that endocrinological abnormalities, in particular hypothyroidism, may also be part of the ARID1B spectrum, but further research is needed to confirm this finding." (PMID 30349098, 2019).